SOX2 (SRY-box transcription factor 2)
Diseases named in the same sentence as SOX2 in open-access papers (continued):
Sharing a sentence is not in itself a finding about the gene and the disease.
tumor (continued). "Single-cell analysis revealed high expression of SPHK1 in tumor cells (SOX2, KRT18) and cancer-associated fibroblasts (COL1A2 and MMP2) and low expression in cancer stem cells (PROM1)." (PMID 39629135, 2024). "SOX2 overexpression is associated with increased tumor growth and resistance to differentiation, emphasizing its significance in GBM pathogenesis." (PMID 39063221, 2024). "SOX2, indeed, crosstalks with multiple signaling pathways to tightly regulate critical biological processes associated with tumor initiation and progression, such as cell-cycle, apoptosis, autophagy, and epithelial-to-mesenchymal transition (EMT)." (PMID 38096163, 2023). "Emerging evidence has revealed that SOX2 protein levels are closely linked with tumor-associated processes, including tumorigenesis, tumor maintenance, invasion, and metastasis." (PMID 37891174, 2023). "To validate this notion in vivo, we inoculated β8-deficient, SOX2 promoter-GFP tumor cells (~800 Pa stiffness) into mice." (PMID 37614365, 2023). "Recently, SOX2 has been implicated in the pathogenesis of GC, functioning as a tumor suppressor that reduces GC cell proliferation and metastasis while also promoting apoptosis 16,31,33,34." (PMID 36778127, 2023). "Oct3/4, SOX2 and c-myc are linked to the formation of GSCs, carcinogenesis and tumor progression, which play pivotal roles in the maintenance of GSCs phenotype and stemness." (PMID 36646875, 2023). "High level of SOX2 expression in GBM has been associated with tumor aggressiveness and worse prognosis." (PMID 37047365, 2023). "To assess the impact of the loss of SOX2 expression in the tumor initiation capacity of enhancer-deleted cells, we performed a colony formation assay with MCF-7 and PC-9 ΔENH–/– cells." (PMID 37738673, 2023). "The association between SOX2 immunoexpression and advanced tumor size was found to be significant (OR = 0.25; 95% CI 0.14–0.45, p < 0.00001, I2 = 0%)." (PMID 37109090, 2023). "Higher expression of N-cadherin, Vimentin, Snail, and Sox2 and lower expression of E-cadherin are always associated with tumor metastasis." (PMID 37745054, 2023). "For its ability to replace both Sox2 and c-Myc (whose absence reduced tumor formation risk), E-616452 was chosen for further characterization and given the name RepSox—Replacement of Sox2." (PMID 36983843, 2023). "Martinez-Barbera showed that the CTNNB1 mutation occurs only in SOX2+ pituitary tumoral stem cells which represent the “true” tumoral cells and lead to the tumor development in a paracrine manner." (PMID 36979325, 2023). "The causative effect of BRAFV600E mutation is not clear, but it seems to involve a proliferative advantage to tumor SOX2+ cells with a mutated differentiation potential." (PMID 36979325, 2023). "The six key-gene signature (ADRB2, DPYSL2, IL7R, LIMCH1, PIK3R1 and SOX2) has been shown to be associated with metastasis and progression of many tumor types through molecular experiments." (PMID 38057344, 2023). "The heterogeneity was the least (0%) while evaluating the association of transcriptional CSC markers with grading, SOX2 immunoexpression with tumor size, and CSC/transcription markers immunoexpression with overall survival." (PMID 37109090, 2023). "SOX2 expression is associated with sphere formation, tumor initiation, cell proliferation, migration, drug resistance, and the expression of stemness-related and EMT-related genes in BC and OC." (PMID 37445860, 2023). "C-myc, Nanog, Oct-4 and Sox-2 are all tumor-associated genes, and the core transcriptome of Nanog, Oct-4 and Sox-2 is involved in the self-renewal of CSCs." (PMID 38095348, 2023). "Akt plays a critical role in self-renewal by directly promoting Oct4 and Sox2 upregulation in cancer cells which is associated with tumor initiation and apoptosis resistance." (PMID 36359223, 2022). "Mutations activating the MAPK signalling pathway result in tumour formation, showing an increase in proliferation of SOX2+ cells and impairment of differentiation." (PMID 36451046, 2022).
tumor (continued). "Tumor development was significantly slowed down in the Sox2-deficient mice compared to the other groups, and the survival rate was also higher in the Sox2 knockout mice." (PMID 35582537, 2022). "As SOX2 functions as a transcription factor in promoting the cancer stem cell phenotype, this suggests that the tumor-suppressing effects of TGF-β are associated with SOX2 inhibition of lncRNA H19 transcription in TICs." (PMID 36467404, 2022). "Consistent with the growth inhibitory effects of SOX2 during development, high levels of SOX2 expression within a tumor are associated with slow cycling/infrequently proliferating cancer stem cells." (PMID 35454854, 2022). "Treatments with inhibitors that target the upstream SHH signaling components, such as the SMO inhibitor vismodegib, cause an enrichment of tumor-associated astrocytic SOX2+ cells resulting in an increased chance of relapse." (PMID 36291792, 2022). "IHC analysis showed that overexpression of RICH1 significantly inhibited the expression of YAP/TAZ and CSCs-associated markers (ALDH1A1, NANOG, OCT4, and SOX2) in transplanted tumor tissues." (PMID 35064101, 2022). "These lipoplexes also reduced tumor volume in mice, suggesting that such effects were attributed to the crucial role of SOX2 in the regulation of signaling pathways associated with CSCs." (PMID 35163777, 2022). "SOX2 was reported to regulate T cells and tumour‐associated neutrophils, as well as fine‐tunes cancer immunity." (PMID 35415876, 2022). "As well as STAT3, it has been shown that suppression of STAT1 reduces the formation of lung A549 tumor spheres which was maintained by the suppression of factors associated with stemness, such as SOX2, OCT4, and NANOG." (PMID 35205716, 2022). "The studies reported here set out to investigate the underlying mechanisms through which elevated SOX2 restricts tumor cell proliferation." (PMID 35454854, 2022). "High FMOD in either stroma or tumor was significantly associated with high SOX2 expression and this relationship held when cerebral lesions were examined separately (t test, p = 0.02 and p = 0.0002, respectively)." (PMID 35737114, 2022). "Aberrant Sox-2 expression is associated with many malignancies and has well-characterized roles in tumor growth, metastasis, and drug resistance." (PMID 34546978, 2021). "Hypomethylation of binding sites for stemness- and proliferation-associated transcription factors (Oct4, Nanog, Sox2) was detected in circulating tumor cells that formed clusters linked to increased metastatic potential." (PMID 34299205, 2021). "Through MAPK activation, the mutation can transform normal SOX2+ stem cells in the pituitary into PCP tumor initiation cells." (PMID 34660308, 2021). "In many types of cancer, SOX2 is dysregulated due to overexpression associated with tumor progression and low survival rate." (PMID 34436030, 2021). "Resistance to anti-tumor therapy is associated with SOX2-mediated activation of ABC transporters, which are able to efflux drugs across the cell membrane by utilizing ATP8,14." (PMID 33953166, 2021). "These complex mechanisms can be associated with a variety of cytokines, such as IL‐6 and Sox2, which give diffuse GC a unique tumor immune environment." (PMID 33410261, 2021). "The overexpression of Sox2 in YAP null cells rescues the loss of CSCs and tumor growth features, suggesting that Sox2 is the essential downstream effector of YAP." (PMID 34439395, 2021). "Hypomethylation activates oncogenes along with some tumour associated genes such as SOX-2, Oct-4, IGF-2, etc.." (PMID 34685742, 2021). "A recent meta-analysis has shown that SOX2 overexpression is significantly associated with inferior overall survival, distant metastasis, poor differentiation, and advanced tumor stage in patients with CRC." (PMID 34833970, 2021). "SOX2-positive ATCs were associated with nodal metastasis, capsular invasion, extrathyroid extension, vascular invasion, positive margins, and large-sized tumours." (PMID 33489519, 2020).
tumor (continued). "Specifically, the high expression levels of CD133 and SOX2 play a crucial role in the acquisition of metastatic phenotype by tumor cells, and are also implicated in cancer cell differentiation." (PMID 32754302, 2020). "This was confirmed by multivariate analysis, as Sox2 was associated with higher probabilities of distant metastasis (HR = 2.01, 95% CI 1.08–3.75, p = 0.0288), independently of tumor size and AR expression (p = 0.0021, Cox proportional-hazard regression)." (PMID 33553286, 2020). "Collectively, these studies in multiple tumor cell lines, representing four human tumor types, demonstrate that elevating SOX2 decreases expression of cyclins and/or CDKs associated with each phase of the cell cycle." (PMID 32998722, 2020). "STAT3 was also reported to mediate Sox2 expression in murine breast cancer cells in response to tumor-associated macrophages." (PMID 33228022, 2020). "The AR+Sox2– phenotype was associated with low probabilities of cancer-related death independently of tumor size, nodal and distant metastasis." (PMID 33553286, 2020). "SOX2 was associated with tumor progression of many tumors such as gastric, pancreatic, breast, colorectal cancers, and osteosarcomas." (PMID 33112555, 2020). "In CRC, SOX2 overexpression has been associated with tumor progression and disease recurrence and SOX2 de novo expression was associated with poorly differentiated and more invasive tumors and poor patient overall survival." (PMID 32626705, 2020). "In most of these cancers, SOX2 expression is associated with their respective tumor-initiating/cancer stem cell populations and thus, disease progression and negative outcomes." (PMID 32998722, 2020). "In the 123 triple-negative FMCs, Sox2 expression showed a positive association with the clinical tumor size, dermal infiltration, the Ki-67 proliferation index, AR expression, and intratumoral Treg numbers." (PMID 33553286, 2020). "Similar to the effects of SOX2 during development, elevated levels of SOX2 are associated with quiescent tumor-initiating cells." (PMID 32998722, 2020). "Positivity to Sox2 has been associated with a larger tumor size, presence of lymph node metastasis, a higher histological grade, a higher Ki-67 proliferation index, and negativity to Estrogen Receptor (ER) and Progesterone Receptor (PR)." (PMID 33553286, 2020). "The recruitment of tumor-associated neutrophils in NSCLC involves SOX2-mediated production of CXCL535." (PMID 32632106, 2020). "SOX2 expression has also been implicated in different biological processes that regulate tumor progression, such as cell proliferation, migration, invasion, tumorigenesis, antiapoptosis, and chemoresistance." (PMID 32635524, 2020). "Sox2 has been implicated in tumor initiation, epithelial-to-mesenchymal transition (EMT), and resistance to therapy and metastasis in several human cancers." (PMID 32290242, 2020). "Collectively, the research on METTL3 and SOX2 suggests that METTL3-mediated m6A modification regulates SOX2-associated stem cell self-renewal and tumor progression." (PMID 31921660, 2019). "SOX2 amplification and overexpression has been implicated in many tumor types, but mostly in squamous carcinomas of various localizations (lung, esophagus, head and neck)." (PMID 30823625, 2019). "The expression of SOX2 is associated with tumor formation, chemotherapeutic resistance and the tumor stem cell like phenotype." (PMID 31718604, 2019). "Accordingly, SOX2 has emerged as a candidate driver gene responsible for the 3q26-associated tumor aggressiveness." (PMID 30823625, 2019). "Prior studies have associated vismodegib failure with tumor stem cells, defined by SOX2 expression, lineage tracing and transplantation experiments." (PMID 31863004, 2019). "For instance, U87MG and LN18 GBM cells cocultured with clinical M2 GAMs showed increased colony-forming and tumor-sphere-generating abilities in association with increased stemness markers Sox2, STAT3, Wnt, and Nestin in the GBM cells." (PMID 31269723, 2019).
tumor (continued). "In this study the nuclear expression of SOX2 was associated with higher histopathological grade of the tumor (p=0.002)." (PMID 31508790, 2019). "Overexpression of these genes (OCT4, NANOG, and SOX2) in human cancer stem cells is associated with tumor transformation, tumorigenicity, and tumor metastasis." (PMID 31375149, 2019). "A relationship between SOX2 overexpression in tumorigenesis has been established in different types of cancer, including prostate and its expression linked to tumor grade." (PMID 29888169, 2018). "We assessed the association of SOX2 signature with tumour site, human papillomavirus (HPV) infection status, regional LN metastasis, T stage, and smoking status." (PMID 29374236, 2018). "The pluripotency-associated transcription factor SOX2 was recently shown to be expressed in a cell population manifesting properties of cancer stem cells or tumour-initiating cells and to be associated with drug resistance." (PMID 29666462, 2018). "NC9 treatment produces a marked reduction in tumor formation and this is associated with a parallel reduction in stem cell (Sox-2, Oct-4) and EMT (fibronectin, N-cadherin, Slug and Twist) marker levels." (PMID 30349644, 2018). "The loss of SOX2, retention of tumor-initiating capabilities, and the ‘switch-like’ behavior observed in HN120 drug-resistant and metastatic counterparts suggested the possibility for a stem cell switch." (PMID 30467425, 2018). "We found that SOX2 expression showed a significant association with tumor status, TNM stage and lymph nodes infiltration." (PMID 30186173, 2018). "Analysis of the tumors showed that the delay in tumor initiation was associated with decreased expression of stem cell marker SOX2." (PMID 28689994, 2017). "The decreased tumour volume was associated with a reduction in the staining of SOX2 and NESTIN-positive cells, overall proliferation and viability that was accompanied by a diminution in tumour vascularization." (PMID 29053791, 2017). "The transcription factors of embryonic stem cells, such as Oct4, Sox2, Nanog, Bmi1, and Klf4, are known to be associated with stemness, epithelial–mesenchymal transition and aggressive tumor behavior." (PMID 28422735, 2017). "There is compelling evidence that SOX2 is associated with the tumor-initiating population of at least three cancers and there is growing evidence for this association in many other cancers." (PMID 28388544, 2017). "In order to resolve the fate of brCSCs within a tumor prior to, during and after chemotherapy, we determined the association between SOX2, cell migration and expression of EMT markers." (PMID 28835684, 2017). "SOX2 is not only expressed in many types of cancer, it has also been implicated in the tumor-initiating populations (proposed cancer stem cell population) of many of these tumors." (PMID 28388544, 2017). "More recently Sox2 was found to be expressed in broader transit-amplifying cells in the antral isthmus, which contribute to tumor development in the antrum with loss of Apc." (PMID 29340033, 2017). "To illustrate this point, we focus on CD133, which has been linked with SOX2 expression and cancer stem cells in many tumor cell types." (PMID 28388544, 2017). "The stemness related genes SOX2, Klf4, Nanog, and Oct4 are expressed in CSCs and are associated with tumor progression." (PMID 28536422, 2017). "In IHC, Oct4, CD133 and EpCAM were independently related to tumor progression, while Sox2 were associated with well or moderate differentiation (all p<0.05)." (PMID 27557490, 2016). "Sox2 is up-regulated in TNBCs and has been implicated in tumorsphere formation and control of tumor initiation." (PMID 26984638, 2016).
tumor (continued). "Taking all this into account, the canonical pathways more significantly altered after SOX2 inhibition are those related with intracellular signaling cascades and amino-acid metabolism pathways associated with tumor propagation." (PMID 27669421, 2016). "SOX2 has also been implicated in the tumor-initiating cell population (the proposed cancer stem cell population) of most of these cancers." (PMID 27145457, 2016). "Multivariate analysis revealed that SOX2 mRNA expression in the primary tumor was significantly associated with LN metastasis." (PMID 26540632, 2016). "According to our previous study, SOX2 expression was found to be correlated to high tumor grade, mutated BRAF and a poor patient prognosis." (PMID 27411517, 2016). "SOX2 and livin expressions were significantly associated with high tumor grade (P = 0.002 and P = 0.007, respectively) and high tumor stage (P = 0.027 and P = 0.033, respectively)." (PMID 28983346, 2015). "Our results indicate that the engineering of artificial DNA-binding domains (DBDs) linked to DNMT3A can be utilized to promote long-lasting SOX2 silencing and represents a promising therapeutic approach to minimize tumor relapse." (PMID 25684141, 2015). "In NPC, SOX2 has been shown to be expressed in over 90% of tumor tissue and the expression is significantly associated with a poorer distant metastasis-free survival." (PMID 25897700, 2015). "SOX2 and livin expressions were significantly associated with tumor grade (P = 0.014 and P = 0.005, respectively)." (PMID 28983346, 2015). "For all examined cases (117 cases), the expressions of SOX2 and livin were significantly associated with high tumor grade (P = 0.002 and P = 0.007, respectively) and high tumor stage (P = 0.027 and P = 0.033, respectively)." (PMID 28983346, 2015). "As the enrichment of stem cell associated markers such as CD133 and SOX2 correlated with tumor initiation capacity, we then determined the expression of these genes." (PMID 26336988, 2015). "OCT4 overexpression was associated with lymphovascular space invasion (p = 0.045), whereas loss of SOX2 expression was correlated with large tumor size (p = 0.015)." (PMID 26706028, 2015). "Previous work showed that the four factor-derived (Oct3/4, Sox2, Klf4, and c-Myc) iPSCs can cause tumor formation on reactivation of c-Myc." (PMID 24979372, 2014). "Aberrant expression of Sox2 in cancer cells has been well documented in a number of tumor types, but the mechanisms underlying this biochemical aberrancy is largely unexplored." (PMID 24885403, 2014). "In our patient cohort, SOX2 expression was found to be significantly associated with a high tumor grade (p = 0.004) and TNM stage (p = 0.034)." (PMID 25010701, 2014). "11% of the tumors were SOX2 positive, and the expression correlated to tumor grade, TNM stage and BRAF mutation." (PMID 25010701, 2014). "To elucidate the role of Sox2 in HCC, we investigated the correlation between Sox2 mRNA expression and clinicopathological variables associated with tumor progression." (PMID 23599755, 2013). "Comparison of the SOX2-interactome described in this study for DAOY MB tumor cells (283 SOX2-associated proteins) with the SOX2-interactome described recently for GB tumor cells (144 SOX2-associated proteins) shows surprisingly little overlap." (PMID 23667531, 2013). "High nuclear expression of SOX2 was significantly associated with several clinicopathological features including N classification (P = 0.000), M classification (P = 0.043) and tumor stage (P = 0.000)." (PMID 23424657, 2013). "In HCC tissues, aberrant expression of Sox2 and Lin28 was associated with a large tumor size (P=0.02 and P=0.03, respectively), while increased expression levels of c-Myc (P=0.01) were correlated with vascular invasion." (PMID 23599755, 2013).